TERT (telomerase reverse transcriptase)
Diseases named in the same sentence as TERT in open-access papers (continued):
Sharing a sentence is not in itself a finding about the gene and the disease.
cancer (continued). "The transcriptional reactivation of TERT in cancer cells is mediated by many signaling pathways, primarily c-MYC, NF-κB, and B-Catenin." (PMID 40151802, 2025). "In colorectal cancer, hsa_circ_0020397 enhances cell viability and invasion of cancer cells and suppresses their apoptosis by regulating the expression of miR‐138 target genes, including PD‐L1 and TERT." (PMID 39901896, 2025). "We explored two previously reported but minimally characterized VNTRs9,10 within TERT intron 6 in relation to all cancer-related GWAS signals within the 5p15.33 multi-cancer region." (PMID 39956830, 2025). "Approximately 85–90 % of cancer cells use the ribonucleoprotein, telomerase, containing a catalytic subunit (TERT) and an RNA template (TERC) to add sequential TTAGGG telomeric repeats to the ends of chromosomes." (PMID 41321994, 2025). "Mechanisms of tight control of TERT by TL shown here are likely to have major implications in telomere-related physiologies, particularly, cancer, ageing, and pluripotency." (PMID 41026782, 2025). "Telomerase and its associated components, beyond their canonical function in preserving telomere integrity, exert profound influence on cancer initiation and progression, with TERT assuming a particularly central role." (PMID 39871386, 2025). "TERT has emerged as a crucial drug target in cancer research due to its reactivation being essential for the unlimited proliferation potential of human cancer cells." (PMID 40467649, 2025). "TERT facilitates cancer cell proliferation via multiple pathways, including NF-κB, NRF2, MYC, P21, and NOP2." (PMID 39871386, 2025). "Telomerase reverse transcriptase facilitates cancer growth and cell survival and is overexpressed in many cancers, including LUAD." (PMID 40740860, 2025). "Increasing evidence suggests that TERT, the catalytic subunit of telomerase, exerts additional biological functions that promote cancer progression independently of its role in telomere maintenance." (PMID 40227701, 2025). "From a subcellular perspective, the localization of TERT within cancer cells can serve as a biomarker." (PMID 39871386, 2025). "These varied approaches underscore the significance of TERT as a multifaceted target in cancer therapy." (PMID 40467649, 2025). "In this work, we showed that the genetic regulation of TERT splicing by an SNP rs10069690 and VNTR6-1, a 38-bp intronic tandem repeat, accounts for the reduced or elevated cancer risk associated with multi-cancer GWAS leads rs2242652 and rs10069690 at 5p15.33." (PMID 39956830, 2025). "ZIF-8 enhances the nuclear transport and release of BIBR1532, improving TERT activity inhibition and anti-cancer effects." (PMID 40227701, 2025). "Ninety percent of cancers are characterized by overexpression of telomerase, which counteracts telomere attrition by its telomerase reverse transcriptase (TERT)." (PMID 39762846, 2025). "While the TERT promoter region around the transcription start site typically unmethylated in actively transcribed TERT, hypermethylation of the TERT gene has been shown to correlate with telomerase activity in various cancers." (PMID 41294748, 2025). "To test if TL of cells affected TRF2 occupancy at the TERT promoter, we first elongated telomeres in cancer cells under isogenic backgrounds (termed as Short Telomere, ST, or Long Telomere, LT cells hereon)." (PMID 41026782, 2025). "Numerous TERT-specific compounds designed to inhibit its reverse transcriptase activity have been identified and developed as anti-cancer drugs aimed at limiting tumor growth." (PMID 40467649, 2025). "We and others have previously analyzed telomere maintenance mechanisms, TERT expression, and telomere length across various cancers." (PMID 41321994, 2025).
cancer (continued). "In this review, we provide a comprehensive overview of the extratelomeric functions of TERT in B-cell malignancies, emphasizing their therapeutic potential as novel targets for cancer treatment." (PMID 40227701, 2025). "One prominent example is Telomelysin (OBP-301), a replication-competent oncolytic adenovirus engineered with a TERT promoter, enabling selective replication in telomerase-positive cancer cells." (PMID 40227701, 2025). "Recently, novel cancer drugs with sex bias like telomerase reverse transcriptase (TERT) modulators are emerging, while drugs targeting sex-related genetic factors like telomerase inhibitors still require further investigation." (PMID 40303343, 2025). "Our findings offer valuable insight into the pathological effects of TERT expression in cancer cells, beyond its role in telomere maintenance." (PMID 39975037, 2025). "Cancer-specific hypermethylation within the TERT Hypermethylated Oncological Region (THOR) and the broader CpG island termed “Acheron” correlates with hTERT reactivation, tumor progression, and adverse outcomes." (PMID 41375001, 2025). "In cancer cells, a TERT hypermethylated oncological region (THOR) is located distal of the transcription start site (TSS)." (PMID 39871386, 2025). "Most cancer cells, in contrast to normal adult somatic cells, maintain telomeres through reactivation of TERT (~90% of cancers); alternative lengthening of telomeres (ALT) is used in other cases." (PMID 41026782, 2025). "As the core catalytic subunit of telomerase, telomerase reverse transcriptase (TERT) plays essential roles in the tumorigenesis and development of various cancers." (PMID 39901896, 2025). "Given the high prevalence of TERT alterations in different cancer types, there have been ongoing efforts to target components of the telomerase holoenzyme." (PMID 40272676, 2025). "At least ten independent GWAS signals within the ~100 kb genomic region on chromosome 5p15.33 harboring TERT and CLPTM1L have been associated with cancer risk or protection." (PMID 39956830, 2025). "A systematic analysis of TERT high and low cancers using multidimensional data from TCGA depicts a telomerase-associated molecular landscape in cancers." (PMID 41294857, 2025). "The mRNA expression levels of RHAMM and TERT are positively correlated (p < 0.05) across ten types of human cancer and cancer cell lines, obtained from the TCGA Pan-Cancer Atlas database." (PMID 40661163, 2025). "Lastly, TERT-derived vaccines have emerged as a promising approach to elicit an immune response against various cancers." (PMID 40025596, 2025). "The genomic region 5p15.13 is known to harbour many cancer susceptibility variants with at least two possible candidate genes CLPTM1L and TERT." (PMID 40321259, 2025). "Abnormal activation of telomerase reverse transcriptase (TERT) in cancer cells enables them to escape cellular senescence and thereby acquire unlimited proliferation ability." (PMID 40666524, 2025). "Genes at two of these loci, HERC2/OCA2 and IRF4, are involved in pigmentation, while the third, CLPTM1L/TERT, is a known cancer driver." (PMID 40495383, 2025). "At the subcellular level, upon exposure to exogenous stress, TERT transfer from the nucleus to mitochondria in cancer cells." (PMID 39871386, 2025). "This was also validated by our data showing that BRAF kinase inhibitor PLX4032 significantly down-regulated protein and mRNA levels of TERT and c-Myc in BRAFV600E/pTERT double mutated cancer cells 8305C and A375." (PMID 40860184, 2025). "The development of TERT inhibitors has become a pivotal focus in anticancer therapy due to their potential to restrict the immortality of cancer cells." (PMID 40467649, 2025).
cancer (continued). "TERT induces cancer cell dedifferentiation, and a proposed mechanism of action is mediated by enhanced ribosome biogenesis." (PMID 40361475, 2025). "Small-molecule ligands can limit cancer telomere lengthening by targeting telomere G4 (a guanine-rich sequence of the telomeric DNA) and TERT." (PMID 40332222, 2025). "Since TERT is specifically and highly expressed in cancer cells, hTERT has been a therapeutic target for cancer drug discovery and development." (PMID 40281695, 2025). "TERT promoter mutant (TPM) cancer cells are characterized by gene expression signatures matching RAS pathway driven states, although many of these are not explained by mutations known to activate the RAS pathway." (PMID 40560846, 2025). "The molecular and genetic alterations in DTC, such as BRAF:p.V600E, RAS mutations, TERT promoter mutations, and RET/PTC rearrangements, provide valuable diagnostic and prognostic insights into these carcinomas." (PMID 40940966, 2025). "Allelic DNA methylation within the TERT promoter further contributes to the regulation of TERT expression in cancer." (PMID 38278800, 2024). "Hypomethylation of specific regions can lead to repression and activation of TERT expression, as seen in various cancers." (PMID 39126110, 2024). "One possibility is the disruption of TERT gene function, resulting in decreased telomerase activity in cancer cells." (PMID 38195537, 2024). "Regions that were significantly amplified in CS-like tumors held many genes known to be associated with cancer development, including KRAS, CDK4, and TERT." (PMID 38978078, 2024). "For unlimited proliferation of cancer cells, they must express telomerase reverse transcriptase (TERT) to maintain telomere length, preventing DNA shortening during replication, and achieving immortality." (PMID 39131044, 2024). "Here, we explored two VNTRs within TERT intron 6 in relation to the cancer-related GWAS signals reported in this region." (PMID 39802763, 2024). "TERT’s role in nuclear–mitochondrial communication helps cancer cells avoid DNA damage-induced apoptosis, highlighting its multifaceted functions in cancer cell adaptation and survival." (PMID 39126110, 2024). "BL is an aggressive pediatric cancer originating from germinal center B cells, in which high TERT expression is necessary for the longevity of memory B cells." (PMID 39802763, 2024). "TERT plays a significant role in cancer formation, which is a limiting factor in the production of telomerase complexes in cancer cells." (PMID 38819232, 2024). "Gene copy number variation in TERT has been documented in cancer cases where gene amplifications of TERT were observed in somatic tissue samples." (PMID 39206265, 2024). "Previous research has shown that TERT activity is increased in many cancer cells and helps the cells divide indefinitely." (PMID 38495498, 2024). "Reacting the TERT is crucial for maintaining telomeres, and thus for supporting the uncontrolled division of cancer cells." (PMID 39228402, 2024). "Mutant TERT promoters, commonly detected in various types of cancer, induce TERT overexpression by recruiting transcription factors that do not normally regulate TERT gene expression and promoting abnormal telomerase activation." (PMID 38278800, 2024). "Our recent study showed that FOS inhibitor T‐5224 suppressed the growth of TERT mutant cancer cells through downregulating GABPB and the transcription of TERT in the presence of TERT promoter mutation." (PMID 38769666, 2024). "CRISPR-Cas9 can be employed as a gene-editing tool to target and modify the TERT gene in cancer cells." (PMID 38195537, 2024). "In this review, we focus on the regulators of TERT and these downstream functions in cancer regulation." (PMID 38278800, 2024).
cancer (continued). "The dietary component of genistein is a potential therapeutic molecule within a TERT-targeting cancer treatment strategy." (PMID 38278800, 2024). "The expression of TERT endows cancer cells with replicative immortality, allowing oncogenic proliferation to persist indefinitely." (PMID 39095874, 2024). "TERT activity is typically carefully regulated, but changes can disrupt this control, resulting in unregulated cell proliferation and cancer development." (PMID 38667446, 2024). "And increasingly recent studies identified that TERT is also involved in cancer progression in a telomere-independent manner." (PMID 38313800, 2024). "In contrast, the level of 40 positive cell cycle regulator proteins and a set of epithelial-to-mesenchymal transition pathways was specific for the TERT- group suggesting different proliferation strategies for both groups of cancer." (PMID 38859942, 2024). "For example, the ubiquitously amplified TERT gene implicates telomerase inhibition as a possible broad-spectrum cancer treatment approach." (PMID 38495498, 2024). "We explored two previously reported but only minimally characterized VNTRs7,8 within the TERT intron 6 in relation to all cancer-related GWAS signals within the multi-cancer 5p15.33 region." (PMID 39802763, 2024). "They concluded that TERT expression in cancer lines is canonical in respect to hypomethylation, despite the occurrence of an unusual upstream located hypermethylated region." (PMID 39000438, 2024). "We found that the FLT3LG exGS was largely explained by trans-pQTL that lie in established cancer risk genes involved in the regulation of cell division and DNA repair (CHEK2 [22:28695868:AG:A], ATM [11:108267276:T:C], and TERT [5:1293971:C:T])." (PMID 38750076, 2024). "TERT was a catalytic subunit of telomerase, and played an important role in cancer proliferation, invasion, and DNA damage response." (PMID 38890738, 2024). "The mutation frequencies in BRAF, TERT, RET, ATM and GGT1 were significantly higher in cancer tissues than benign nodules." (PMID 38886866, 2024). "Another study showed that increased TERT expression in cancer-resistant mice delayed ageing and prolonged survival by 40%." (PMID 38256704, 2024). "The co-interacting factors play an important role in the regulation of TERT in different cancer types." (PMID 38278800, 2024). "Telomerase (TERT), a reverse transcriptase that can repair shortened telomeres, is less common in somatic cells and more prevalent in cancer cells." (PMID 38972884, 2024). "Clinical and pathological characteristics of the 31 925 patients with cancer and available TERT sequencing data." (PMID 37462445, 2024). "Therein, 32/38 (84%) of DNA repair pathways were hyperactivated in TERT+ cancers which was also connected with accelerated replication, transcription, translation, and cell cycle progression." (PMID 38859942, 2024). "Mutations in the promoter of the catalytic subunit of the telomerase reverse transcriptase (TERT) gene are frequently observed in several cancers and drive telomere maintenance." (PMID 38612507, 2024). "The impact of functional circulating TAA reactive T cells on survival has already been mentioned previously, as well as by our group after vaccination with a cryptic TERT vaccine in different cancer types, including NSCLC." (PMID 39001455, 2024). "In many cancers, tumors achieve unlimited replicative potential primarily by activating the enzyme telomerase through increased transcription of the TERT gene." (PMID 39409990, 2024). "Owing to their good anti-cancer properties, TERT and telomerase are used as therapeutic targets for telomerase-positive cancer." (PMID 38278800, 2024).
cancer (continued). "In human cancer cell lines, TERT physically forms a complex with BRG1, a SWI/SNF-related chromatin remodeling protein, and nucleostemin, a nucleolar GTP-binding protein." (PMID 38278800, 2024). "The chromosome 5p15.33 region, which encodes telomerase reverse transcriptase (TERT), harbors multiple germline variants identified by genome-wide association studies (GWAS) as risk for some cancers but protective for others." (PMID 39802763, 2024). "Mechanistically, Sp1, the transcription factor of VEGF, interacts with TERT and facilitates angiogenesis in cancer via VEGF activation." (PMID 38278800, 2024). "TERT gene activation and telomerase activation are related to cell proliferation and regulation, and therefore, anti-cancer drugs that target TERT amplification can be used to treat cancer." (PMID 39669196, 2024). "For instance, the ubiquitously amplified TERT gene implicates telomerase inhibition as a possible broad-spectrum cancer treatment approach." (PMID 38495498, 2024). "PTMs increase the biochemical diversity of TERT functions, thereby affecting telomerase regulation in cancer cells." (PMID 38278800, 2024). "Due to its role in maintaining telomere length, TERT is crucial for the stability of stem cells and cancer cells." (PMID 39430380, 2024). "Methylation of the TERT promoter has been extensively studied, especially in various cancers, and is often characterized by hypermethylation." (PMID 39296334, 2024). "For over 20 years, TERT has been recognized that TERT is a target for cancer treatment because of its exclusive expression in cancer cells." (PMID 39239547, 2024). "Telomerases are HLA class-I antigens, hence TERT-derived vaccines have also been considered as an approach to stimulate immune response in targeting cancers." (PMID 38278800, 2024). "Based on CD4+/CD8+ T cell recognition, the TERT vaccine presents a promising therapeutic efficacy in a proportion of cancer, although its safety and universal applicability in different types of cancer requires further research and verification." (PMID 38278800, 2024). "Telomerase reverse transcriptase (TERT) gene promoter mutations have been explored, as biomarkers of improved survival for patients with cancer receiving immune checkpoint inhibitors." (PMID 37462445, 2024). "Research demonstrates that TERT plays a crucial role in cancer development, and its expression is regulated by different miRNAs." (PMID 39769169, 2024). "Functionally, TERT affects cancer formation mostly by maintaining telomere length and enabling cells to avert cell senescence." (PMID 38278800, 2024). "FOXD2-AS1 serves as a ceRNA for miR-7-5p and overexpresses the telomerase reverse transcriptase (TERT), which increases cancer stem cell characteristics." (PMID 38485838, 2024). "Regarding transcriptional activation, cancer cells often upregulate transcription factors that directly or indirectly increase TERT expression." (PMID 39126110, 2024). "TERT transcriptional silencing during the differentiation of stem cells and its activation during the transformation of somatic into cancer cells remains incompletely understood." (PMID 38275760, 2024). "For an additional 2 carcinomas with RAS variants, 1 in ATC was found coexisting with both BRAF V600E and TERT promoter variants, and the other in MTC coexisting with BRAF V600E alone." (PMID 38758552, 2024).